TRGJ1 (T cell receptor gamma joining 1)
Description:
J region of the variable domain of T cell receptor (TR) gamma chain that participates in the antigen recognition. Gamma-delta TRs recognize a variety of self and foreign non-peptide antigens frequently expressed at the epithelial boundaries between the host and external environment, including endogenous lipids presented by MH-like protein CD1D and phosphoantigens presented by butyrophilin-like molecule BTN3A1. Upon antigen recognition induces rapid, innate-like immune responses involved in pathogen clearance and tissue repair. Binding of gamma-delta TR complex to antigen triggers phosphorylation of immunoreceptor tyrosine-based activation motifs (ITAMs) in the CD3 chains by the LCK and FYN kinases, allowing the recruitment, phosphorylation, and activation of ZAP70 that facilitates phosphorylation of the scaffolding proteins LCP2 and LAT. This lead to the formation of a supramolecular signalosome that recruits the phospholipase PLCG1, resulting in calcium mobilization and ERK activation, ultimately leading to T cell expansion and differentiation into effector cells. Gamma-delta TRs are produced through somatic rearrangement of a limited repertoire of variable (V), diversity (D), and joining (J) genes. The potential diversity of gamma-delta TRs is conferred by the unique ability to rearrange (D) genes in tandem and to utilize all three reading frames. The combinatorial diversity is considerably increased by the sequence exonuclease trimming and random nucleotide (N) region additions which occur during the V-(D)-J rearrangements.
Synonyms: TCRGJ1; J1
Gene: T-cell receptor joining (J) gene on chromosome 7 (38,269,491 to 38,269,540, reverse strand). Ensembl gene ENSG00000211690.
Subcellular location: Cell membrane
Gene Ontology:
Cellular component: plasma membrane